RNU1-21P (RNA, U1 small nuclear 21, pseudogene)
Gene: Small nuclear RNA gene on chromosome 11 (123,763,927 to 123,764,089, forward strand). Ensembl gene ENSG00000200197.
Homologues: Orthologues: chimpanzee U1 (99% identical). Paralogues in human: RNU1-1 (90% identical), RNU1-2 (90% identical), RNU1-27P (90% identical), RNU1-28P (90% identical), RNU1-3 (90% identical), RNU1-4 (90% identical), RNVU1-18 (90% identical), RNVU1-29 (90% identical), RNVU1-31 (90% identical), U1 (90% identical), RNU1-83P (89% identical), RNVU1-28 (89% identical), and 134 more.